SLC4A9 (solute carrier family 4 member 9)
Description:
Electroneutral Cl(-)/HCO3(-) antiporter that favors chloride ion entry and efflux of hydrogencarbonate and sodium ion across the basolateral membrane and may participate in salivary secretion. Also mediates Cl(-)/HCO3(-) exchange activity in the presence of K(+) as well as Cs(+), Li(+), and Rb(+) (By similarity). Does not contribute to Cl(-)/HCO3(-) exchanger in the apical membrane of the upper villous epithelium (By similarity).
Synonyms: AE4
Tractability: Antibody: its Gene Ontology location is reachable by antibodies, with high confidence; UniProt places it where antibodies can reach, with medium confidence; UniProt predicts a signal peptide or a membrane-spanning region; the Human Protein Atlas places it where antibodies can reach.
Gene: Protein-coding gene on chromosome 5 (140,360,188 to 140,375,143, forward strand). Ensembl gene ENSG00000113073.
Subcellular location: Basolateral cell membrane
Subcellular location (Human Protein Atlas): Cytosol; Plasma membrane; Vesicles
Pathways (Reactome):
Transport of small molecules: Bicarbonate transporters
Gene Ontology:
Molecular function: chloride:bicarbonate antiporter activity; sodium:bicarbonate symporter activity; monoatomic anion transmembrane transporter activity; sodium,bicarbonate:chloride antiporter activity; solute:inorganic anion antiporter activity
Biological process: bicarbonate transport; regulation of intracellular pH; sodium ion transmembrane transport; chloride transmembrane transport; monoatomic anion transmembrane transport; monoatomic anion transport; saliva secretion
Cellular component: basolateral plasma membrane; plasma membrane; apical part of cell; membrane
Genetic constraint (gnomAD): Loss-of-function variants: 97 observed, 95.49 expected, observed/expected ratio (o/e) 1.02, 90% interval 0.86 to 1.2. The upper end of that interval is the gene's LOEUF score, 1.2, which puts it in group 5 of 6, group 1 being the genes least tolerant of losing a copy. Missense variants: 1,072 observed, 1,148.1 expected, observed/expected ratio (o/e) 0.93, 90% interval 0.89 to 0.98. Synonymous variants: 445 observed, 460.48 expected, observed/expected ratio (o/e) 0.97, 90% interval 0.89 to 1.04.
Homologues: Orthologues: chimpanzee SLC4A9 (99% identical), macaque SLC4A9 (98% identical), rabbit SLC4A9 (87% identical), dog SLC4A9 (86% identical), pig SLC4A9 (84% identical), rat Slc4a9 (82% identical), mouse Slc4a9 (82% identical), guinea pig SLC4A9 (82% identical), tropical clawed frog slc4a9 (54% identical), Caenorhabditis elegans abts-1 (40% identical), Drosophila melanogaster Ndae1 (40% identical), Drosophila melanogaster Ae2 (30% identical), and 1 more. Paralogues in human: SLC4A4 (52% identical), SLC4A5 (50% identical), SLC4A10 (45% identical), SLC4A7 (45% identical), SLC4A8 (45% identical), SLC4A2 (36% identical), SLC4A3 (35% identical), SLC4A1 (33% identical), SLC4A11 (22% identical).
Diseases named in the same sentence as SLC4A9 in open-access papers:
SLC4A9 is named in the same sentence as 5 diseases in open-access papers, as found by Europe PMC text mining. Sharing a sentence is not in itself a finding about the gene and the disease. The quoted sentences say what the papers report.
adenoma (2 papers, 2022 to 2023). A neoplasm arising from the epithelium. "Cystic fibrosis transmembrane regulator (CFTR), downregulated in adenoma (DRA, SLC26A3), putative anion transporter 1 (Pat‐1, SLC26A6) and anion exchanger 4 (AE4, SLC4A9), which transport Cl−/HCO3− to control pHi." (PMID 37638698, 2023). "This is achieved via CFTR and apical Cl-/HCO3- exchangers: downregulated in adenoma (DRA, Slc26a3), putative anion transporter 1 (PAT-1, Slc26a6), and anion exchanger isoform 4 (AE4, Slc4a9)." (PMID 36006975, 2022).
tumor (2 papers, 2023). "In contrast, SLC4A9 has been identified to cause acidification in neoplastic cells and inhibit tumor progression by blocking the hypoxia-induced transport of bicarbonate, thereby exhibiting a protective role, which aligns with our bioinformatic discoveries." (PMID 37812215, 2023).
SLC4A9 also shares sentences with these, for which no sentence is quoted: Alkalosis (1 paper); cancer (1); Hypokalemia (1).